CCND1 (cyclin D1)
Diseases named in the same sentence as CCND1 in open-access papers (continued):
Sharing a sentence is not in itself a finding about the gene and the disease.
breast cancer (continued). "CCND1 copy gain occurs in about 15 -20% of breast tumors and its mRNA and protein was found overexpressed inapproximately 50% of breast cancers, suggesting that other mechanisms than CNAs areinvolved in its expression regulation (Buckleyet al., 1993; Gillettet al., 1994; Maiaet al., 2015)." (PMID 30816904, 2019). "The biological significance of the AR-induced inhibition of cyclin D1 expression is highlighted by clinical studies in ERα-positive breast cancers, showing a better response to adjuvant therapy in cancer patients with cyclin D1 low/moderate expression than those with high expression of cyclin D1." (PMID 31684907, 2019). "Furthermore, Met, CD44, and TCF1/7 were also preferentially expressed in BLBC clinical samples while Cyclin D1 was preferentially expressed in luminal breast cancer clinical samples." (PMID 31462314, 2019). "Notably, miR-193b functions as a tumor suppressor in melanoma, pancreatic cancer, breast cancer, and prostate cancer by suppressing targets including uPA, Mcl1, and cyclin D1." (PMID 32038504, 2019). "However, it is still unclear how BRCA1 and CCND1 expression levels affect the effect of T cell activation on breast cancer patient survival." (PMID 31023256, 2019). "Importantly, LINC01355-mediated suppression of breast cancer growth was reversed by knockdown of FOXO3 or overexpression of CCND1." (PMID 31243265, 2019). "In keeping with our aim to comprehensively determine the long-term prognostic and treatment predictive capacity of CCND1 amplification, we analysed two cohorts of 1965 and 340 breast cancer patients respectively, with matching gene expression, SNP arrays and long-term (15 years) clinical follow-up." (PMID 30819233, 2019). "AGR2 was shown to induce expression of cyclin D1 in breast cancer cells." (PMID 30665445, 2019). "Our molecular characterization of BRCA1-deficient lacrimal acinic cell carcinoma using immunohistochemistry showed that proliferating acinic cells overlapped with the expression of cyclin D1, revealing a property in common with BRCA1-associated mammary tumors in mice." (PMID 30652068, 2018). "CCND1, a putative oncogene on chromosome 11q13, is amplified and overexpressed in many neoplasms, such as squamous cell carcinoma in head and neck, ovarian cancer, breast cancer, and neuroblastomas." (PMID 29416789, 2018). "In addition, the cyclin D1 downregulation by TY-NS-B was observed in human breast cancer cells (MDA-MB-231), human pancreatic cancer cells (AsPC-1), human non-small cell lung cancer cells (A549) and human prostate cancer cells (PC-3)." (PMID 29925351, 2018). "The IL-6/JAK-STAT3/Cyclin D1 axis is activated in biopsies from breast cancer patients." (PMID 30135434, 2018). "In addition to that, overexpression of β-catenin and Wnt pathway targeted gene, cyclin D1 were found to serve as poor prognostic markers in human cancer especially in breast cancer." (PMID 29433490, 2018). "In addition to suppressing IGF1R levels in breast cancer cells, caffeine reduced the key downstream effector pAkt levels as well as the growth promoting ER and cyclin D1 abundance in ER+ cells in vitro." (PMID 29928262, 2018). "The PI3K/Rac/Erk-dependent induction of cyclin D1 previously observed in breast cancer cells may involve P-Rex1-independent pathways that are mediated by the NF-κB pathway." (PMID 29983884, 2018). "Cyclin D1 is overexpressed in 50% of breast cancers, and at lower frequencies in many other cancers including prostate cancer; while Cyclin E has been reported to be deregulated in malignant tumors of the lung, breast, gastrointestinal tract and in ovarian cancer." (PMID 29568320, 2018). "Cyclin D1 (CCND1) protein is found to be overexpressed in more than 50% of breast cancer cases." (PMID 30361291, 2018).
breast cancer (continued). "A report suggested that P-Rex1 controls the induction of cyclin D1 in breast cancer cells." (PMID 29983884, 2018). "In addition, a correlation between cyclin D1 overexpression and response to bortezomib treatment was also shown in breast cancer." (PMID 30180865, 2018). "Finally, miR-30a also mediates G1 cell cycle arrest by targeting Eya2, concomitant with decreased c-Myc, cyclin A, cyclin D1, and cyclin E expression in breast cancer." (PMID 30158978, 2018). "Cyclin D1 is frequently amplified in human cancers, including breast cancer." (PMID 29670855, 2018). "All novel compounds significantly decreased the concentration of cyclin D1 compared to control value in both tested breast cancer cell lines, but the highest statistically significant decrease was observed after 24 h of incubation with PtPz1 in MCF-7 cells and PtPz5 in MDA-MB-231 cells." (PMID 29862867, 2018). "Evidence from breast cancer mouse models suggests that Cyclin D1, and CDK4 and CDK6 activation contribute to suppressing senescence, as Cyclin D1 ablation in these models after tumor formation led to an onset of senescence in the isolated tumor cells, as did treatment with a CDK4 and CDK6 inhibitor." (PMID 29050219, 2017). "Furthermore, KO of Kdm3a also significantly slows down the polyoma middle T (PyMT) oncogene-induced mammary tumor growth by reducing cyclin D1 expression and cell proliferation." (PMID 29156681, 2017). "The higher anti- proliferative activity of abemaciclib in HR+ cells is consistent with known alterations in many of these cell lines, wherein CCND1 amplification indicates that HR+ breast cancers may be especially reliant on this pathway for tumorigenesis." (PMID 29050219, 2017). "The mRNA for cyclin D1 was increased approximately 32-fold in breast cancer." (PMID 29137220, 2017). "UHRF1 overexpression also increased the proliferation and migration potential of breast cancer cells as exogenous expression of UHRF1 in MDA-MB-231 breast cancer cells facilitated their passage through the cell cycle by induction of cyclin D1 and prevention of apoptosis." (PMID 28881702, 2017). "Together with results acquired above, we hypothesized that the suppressive roles of miR-129 may be attributed to the active pathway of miR-129/ESR1/Let-7b in groups of stem-like cells in breast cancer, dependent on the existence of cyclin d1/DICER1." (PMID 29262559, 2017). "Collectively, we showed that cfDNA could promote the proliferation of HR+ breast cancer cells via the TLR9-NF-κB-cyclin D1 pathway." (PMID 28574818, 2017). "Thus, upregulation of cyclin-dependent kinase inhibitor p21(Cip1) and p27(Kip1), and downregulation of the CDK regulator cyclin D1, the proliferation and tumorigenesis of breast cancer cells would be inhibited." (PMID 28881760, 2017). "Cyclin D1/P21 regulates breast cancer cell migration and invasion through TGFβ pathway." (PMID 28602785, 2017). "Moreover, blockade of autophagy induction also inhibited leptin-induced cyclin D1 expression, indicating that cyclin D1 would be a target molecule for autophagy- and ER signaling-mediated suppression of cell cycle progression by leptin in breast cancer cells." (PMID 29312618, 2017). "Furthermore, we demonstrated the activated p65 via PAK5-mediated phosphorylation interacted with Cyclin D1 promoter to promote cell proliferation of breast cancer cells." (PMID 29041983, 2017). "However, it remains to be elucidated how PAK5 regulates Cyclin D1 in breast cancer cell proliferation." (PMID 29041983, 2017). "Cyclin D1 overexpression is considered a driving force in several types of cancers and cdk inhibitors are being used effectively in the clinic for treatment of ERα+ breast cancer." (PMID 29137223, 2017).
breast cancer (continued). "In addition, miR-17/20 targets the cyclin D1 3’-UTR in MCF-7 breast cancer cells, resulting in cell cycle arrest and suppression of cell proliferation." (PMID 28178652, 2017). "The corresponding gene CCND1 is amplified in approximately 9–30% in breast cancer." (PMID 28528450, 2017). "The oncogenic capacity of cyclin D1 has long been established in breast cancer." (PMID 29140993, 2017). "Herein we show the expression of the cyclin D1 gene is increased in human breast cancer stroma." (PMID 29137220, 2017). "The exposure of PDK1 inhibitor GSK2334470 could eliminate the resistance of ribociclib-tolerance breast cancer cells to this compound, with remarkable reduction of pRB, pCDK2, cyclin A, cyclin D1, cyclin E, pS6, and pRSK2." (PMID 28438180, 2017). "CDK4 and Cyclin D1 may be especially relevant for breast cancer, since evidence suggests that both are important oncogenic drivers for this disease." (PMID 29050219, 2017). "To study the mechanisms of Let-7 dysregulation in breast cancer stem-like cells, we found estrogen treatment increased Let-7b expression level, which could be reversed by either cyclin d1 knockdown or DICER1 knockdown." (PMID 29262559, 2017). "Moreover, it has been shown that cyclin D1 cooperates with p21 to regulate TGFβ-mediated breast cancer cell migration and tumor local invasion." (PMID 28797035, 2017). "The importance of improved understanding of cyclin D1 signaling in cancer has recently been underscored due to the introduction of a new class of antineoplastic drugs, the CDK 4/6 inhibitors targeting cell cycle activation by cyclin D1 in breast cancer and other malignant diseases." (PMID 28528450, 2017). "However, a few ER-negative tumors express cyclin D1, demonstrating that this protein can also have an oncogenic role in hormone-independent breast carcinoma pathways." (PMID 29140993, 2017). "Finally, cyclin D1 was co-overexpressed in nine of 14 breast cancer tissues with MST3 overexpression." (PMID 26910843, 2016). "The data presented here demonstrate that cyclin D1, an important cell cycle control protein and proto- oncogene, inhibits PPARα-mediated gene expression and FA oxidation in both hepatocytes and cell lines derived from hepatocellular and breast cancer." (PMID 27351284, 2016). "Overexpression of CCND1 has been previously reported in many cancers including lung cancers, esophageal squamous cell carcinoma, head and neck cancer, pancreatic cancer, pituitary cancer, and breast cancer." (PMID 27766950, 2016). "Furthermore, we checked the protein level of MUC16, β-catenin and three Wnt downstream genes, Snail, Axin2 and Cyclin D1 in three sets of human breast cancer samples by Western blot." (PMID 27167110, 2016). "We next examined the influence of NEAT1 on the expression of cyclin D1, a well-established human oncogene, which is over-expressed in lung cancer, breast cancer and pancreatic cancer, and over-expression of cyclin D1 is involved in malignant transformation in lung tissue." (PMID 27351135, 2016). "Such a discrepancy may be explained taking into account the ability of androgens to inhibit Cyclin D1 expression in breast cancer cells, whose translation is accelerated by miR-21." (PMID 26862856, 2016). "Also cyclin D1 can independently activate ER and a majority of cyclin D1 overexpressing breast cancers are ER+." (PMID 26857361, 2016).
breast cancer (continued). "DCB-3503 may be used to treat malignancies, such as hepatocellular carcinoma or breast cancer with elevated expression of cyclin D1." (PMID 27596272, 2016). "Similarly, down-regulation of PES in human breast cancer cells inhibits cell-cycle progression during the G1/S transition, dramatically reducing cyclin D1 and up-regulating the CDK inhibitor p27Kip1." (PMID 27440937, 2016). "In breast cancer, several lines of evidence have implicated overexpression of EZH2 and repression of tumor suppressors such as KRT5, KRT6, CDH3, RAD51 paralogs, CDKN1C, FOXC1, Wnt/β-catenin signaling (c-Myc, Cyclin D1, Axin2), RKIP and KLF2." (PMID 27835578, 2016). "Interestingly, cyclin D1 has been found to be highly expressed in GC and many other malignancies such as breast cancer and cutaneous melanoma." (PMID 26791264, 2016). "Cell cycle proteins Cyclin D1 controls the transition from the G1 phase to S phase, and it is commonly upregulated in breast cancer cells, leading to defects in mammary development and contributing to the generation of breast cancer, probably by promoting cell growth." (PMID 27409667, 2016). "We next examined the influence of miR-326 on the expression of cyclin D1, a well-established human oncogene, which is over-expressed in lung cancer, breast cancer and pancreatic cancer, and over-expression of cyclin D1 is involved in malignant transformation in lung tissue." (PMID 26840018, 2016). "We next examined the influence of miR-329 on the expression of cyclin D1, a well-established human oncogene, which is over-expressed in lung cancer, breast cancer and pancreatic cancer, and over-expression of cyclin D1 is involved in malignant transformation in lung tissue." (PMID 26909600, 2016). "CCND1 and ErbB2 have been reported to play an early role in sporadic breast cancer." (PMID 27190992, 2016). "Breast and glioblastoma cancer cells synchronized by serum starvation increased their expression of p27 by 6 to 24 h, whereas expression of cyclin D1 showed a progressive reduction in breast cancer cells and a rather stable level of expression in glioblastoma cells." (PMID 27600331, 2016). "In breast cancer cells, cyclin D1 interacts with cytoskeletal proteins and controls migration." (PMID 27286258, 2016). "Interestingly, Cyclin D1 is a well-characterized occurrence in primary breast cancer and this further highlights the potential importance of the miR-206-Cyclin D1 axis in this malignancy." (PMID 26287251, 2015). "Cyclin D1 is also a direct target for β-catenin in breast cancer cells." (PMID 26404249, 2015). "Moreover, Pak1 mediated phosphorylation of ERα at Ser305 has shown to enhance transactivation of ERα leading to up-regulation of ER-regulated genes, such as cyclin D1, which in turn promote hormone-independent growth of breast cancer cells." (PMID 26218748, 2015). "Furthermore, the methylation state of CpG islands in the promoter region upstream of the miR497-195 cluster was responsible for the down-regulation of those two miRNAs in breast cancer, and direct targets of miR-195-5p included CCND1 and RAF1." (PMID 25888956, 2015). "Among them, Cyclin D1 is a major regulator that governs the entrance of a cell into the proliferative stage of the cell cycle, and its expression is regulated by ERα, which mediates its proliferative action on mammary cancer cells." (PMID 25740706, 2015). "For instance, although CCND1 amplification contributes to CyclinD1 overexpression in breast cancer, high levels of CyclinD1 might result from estrogen receptor." (PMID 25839162, 2015). "Our findings also suggest that cyclin D1 may be a potential target of pomegranate bioactive constituents for the chemoprevention of breast cancer." (PMID 26703530, 2015).
breast cancer (continued). "EVO exerts cytotoxic effects on breast cancer cells, and the effects include cell cycle arrest, a decrease in cyclin D1 expression, and induction of cell apoptosis; Furthermore effects of EVO on human hepatocellular carcinoma and gastric tumors have been proven." (PMID 26207989, 2015). "Our data suggest that etodolac may have utility targeting cyclin D1 in breast cancer and that temporal effects should be considered in using tumor gene expression levels of cyclin D1 as a biomarker." (PMID 26275572, 2015). "However, EVO initiated atypical apoptosis in fibroblasts and breast cancer cells by inducing cell cycle arrest at the G0/G1 phase with reduced amounts of Bcl-2, cyclin D1, and CDK." (PMID 26207989, 2015). "Cyclin D1 was reported to be overexpressed in breast cancer, although there are some concerns whether it may serve as a universal breast cancer prognostic factor due to some contradictory data." (PMID 26404249, 2015). "It has been reported that cyclin D1 induces Dicer expression in vitro and in vivo and vice versa and their expression significantly correlates each other (at least in some subtypes of human breast cancer)." (PMID 25705224, 2015). "Both c-Myc and CCND1 (cyclin D1) were reported to be ASC1 targets in breast cancer cells." (PMID 26544067, 2015). "In conclusion, the results from this window-of-opportunity study indicate a statin induced effect on central cell cycle regulators, in terms of an up-regulated expression of the tumor suppressor p27 and down-regulated expression of the oncogene cyclin D1 in breast cancer." (PMID 25925673, 2015). "Thus we revealed a novel P4 elicited signaling cascade herein (P4-c-Myc-miR-320a- ARPP-19/ERRγ/c-Myc/Cyclin D1) to modulate tamoxifen-resistant breast cancer cells." (PMID 25736597, 2015). "The exact mechanism of interaction between RUNX2 and cyclin D1 in breast cancer is not fully known, although it may have features of those in osteoblasts lineage." (PMID 26404249, 2015). "Indeed, a recent study showed that filamin A promotes migration and invasive potential of breast cancer cells through interaction with cyclin D1." (PMID 25944616, 2015). "Therefore, the downregulation of E2F1, CDK4, cyclin D1 and cyclin D3 and upregulation of p27 and p21 in breast cancer cells likely contributed to the G1 cell cycle arrest induced by 5a." (PMID 25766325, 2015). "We noticed that compared to control, in DMBA-treated animals levels of Cdk4 and Ccnd1 were increased respectively an average ~3.0- and 1.0-fold in adjacent mammary tissues; and an additional ~6.0- and 12.0-fold increase was seen, respectively, for Cdk4 and Ccnd1, in mammary tumors." (PMID 26715507, 2015). "Together, the data suggest that AKT2 is not causal for the metastatic lesion, but that CCND1 likely has a role in the primary breast cancer that is reinforced in the metastatic cancer." (PMID 25970776, 2015). "In the current study, cyclin D1 expression significantly decreased in phenformin-treated breast cancer cells, which suggested that phenformin-induced cell cycle changes might be partly due to the downregulation of cyclin D1." (PMID 26114294, 2015). "Thus, vitamin D3 disrupts the interaction of active β-catenin with the cyclin D1 promoter in breast cancer cells." (PMID 26008979, 2015). "Interestingly, upregulation of nuclear and/or cytoplasmic β-catenin in human breast cancer samples has been correlated with the expression of its target gene - cyclin D1." (PMID 26703530, 2015). "Finally, we showed that the amount of Vav1 expression correlated with the expression of Cyclin D1 and influenced the cell cycle progression in breast cancer cells." (PMID 24905577, 2014).